Y_RNA (Y RNA )
Gene: Miscellaneous RNA gene on chromosome 10 (90,880,040 to 90,880,179, reverse strand). Ensembl gene ENSG00000222305.
Homologues: Orthologues: chimpanzee Y_RNA (98% identical), macaque Y_RNA (87% identical), guinea pig Y_RNA (66% identical), dog Y_RNA (65% identical), guinea pig Y_RNA (64% identical). Paralogues in human: RNY1 (68% identical), Y_RNA (66% identical), Y_RNA (65% identical), Y_RNA (64% identical), Y_RNA (62% identical), Y_RNA (61% identical), Y_RNA (60% identical), Y_RNA (59% identical), RNY1P7 (58% identical), Y_RNA (58% identical), RNY1P11 (57% identical), RNY1P8 (57% identical), and 84 more.